OR8J2 (olfactory receptor family 8 subfamily J member 2 (gene/pseudogene))
Description:
Odorant receptor.
Synonyms: OR8J2P
Gene: Protein-coding gene on chromosome 11 (56,208,985 to 56,215,222, reverse strand). Ensembl gene ENSG00000254658.
Subcellular location: Membrane
Pathways (Reactome):
Sensory Perception: Expression and translocation of olfactory receptors
Homologues: Orthologues: dog OR8J2 (84% identical), dog OR8J2B (84% identical), dog OR8J2C (83% identical). Paralogues in human: OR8J3 (78% identical), OR8J1 (77% identical), OR8K1 (58% identical), OR8K3 (57% identical), OR8U3 (57% identical), OR8K5 (57% identical), OR8U1 (56% identical), OR8G5 (53% identical), OR5B12 (53% identical), OR8D1 (52% identical), OR8G1 (52% identical), OR5AP2 (51% identical), and 84 more.